MEOX1 (mesenchyme homeobox 1)
Diseases named in the same sentence as MEOX1 in open-access papers (continued):
Sharing a sentence is not in itself a finding about the gene and the disease.
neurological disorders (1 paper, 2021). "MEOX1 is involved in overall organism development in humans and mutations in mice result in evidence of congenital neurological disorders." (PMID 33562221, 2021).
MEOX1 also shares sentences with these, for which no sentence is quoted: acute myocardial infarction (1 paper); adult onset asthma (1); Alzheimer disease (1); cardiovascular disease (1); glioblastoma (1); Hypertension (1); hypertrophic cardiomyopathy (1); laryngeal carcinoma (1); lung adenocarcinoma (1); Obesity (1); prostate carcinoma (1); spindle cell neoplasm (1); uterine corpus endometrial carcinoma (1).